VIM (vimentin)
Diseases named in the same sentence as VIM in open-access papers (continued):
Sharing a sentence is not in itself a finding about the gene and the disease.
tumor (continued). "Furthermore, the endogenous expression of c-Met, snail, vimentin and VEGF was suppressed in tumor tissues from U87 xenograft mice treated with paeoniflorin compared with tumor tissues from mice treated with PBS." (PMID 35957872, 2022). "A recent study analyzed whether vimentin on the cell surface could be a biomarker toisolate CTCs in PDAC and observed that this protein was highly expressed inpancreatic tumor cells with a mesenchymal phenotype." (PMID 35107490, 2022). "There was a lot of collagen matrix around the tumor cells, and the immunohistochemical markers of the tumor cells were positive for actin and vimentin but negative for SMA, desmin, and S-100." (PMID 36337871, 2022). "Tumor cells were positive for pan-cytokeratin (Pan CK), synaptophysin, vimentin, and S100 (focal) and negative for CD45, CD99, and desmin." (PMID 36259025, 2022). "Immunohistochemically, tumor cells were positive for CD68 and vimentin." (PMID 35220968, 2022). "In summary, negative vimentin expression correlates with tumor metastasis and worse overall survival." (PMID 35320951, 2022). "In the cold areas for the immune responses, i.e., the tumor without invasion by NK cells, less vimentin signal was detected either." (PMID 36032170, 2022). "Mechanistically, Z-GP-DAVLBH treatment reversed the development of RHGP, decreased the amount of co-opted sinusoidal blood vessels, blocked the recruitment of Gr-1+ MDSCs, and suppressed tumor cell EMT as indicated by the increase in E-cadherin and decrease in vimentin." (PMID 35951441, 2022). "Immunofluorescence results demonstrated the presence of upregulated E-Cadherin, and downregulated Vimentin expressions after miR-4731-5p mimic treatment, indicating that miR-4731-5p could inhibit EMT of tumor cells." (PMID 35379785, 2022). "Moreover, several tumor markers and cell adhesion molecules in tumor tissues of dogs were determined by qPCR: HER-2, E-cadherin, N-cadherin, Vimentin, CEA, CA15-3 and SF." (PMID 36359174, 2022). "Importantly, the tumor spheroids derived from the MCW-OV-SL-3 cell line expressed high levels of c-Kit, PROM1, ZEB1, SNAI, VIM, and Twist1 compared to 2D monolayer cells." (PMID 35205706, 2022). "In contrast to typical CTCs and CTECs, a large amount of CRC subtypes have tumor biomarkers, CD31 and Vimentin expressed in pair with abnormal multiple chromosomes; another subtype of diploid CRC with CK18/CD31/Vimentin-positive staining simultaneously was also observed in this study." (PMID 35311070, 2022). "It is interesting to note that this analysis did not indicate any predicted activation relationships; rather, relationships related to inhibition (for seven proteins: LMNA, NME1, PKM, S100A4, SERPINA1, VIM, and AHCY) were indicated for both increased and decreased proteins in the tumor." (PMID 35512017, 2022). "We report that vimentin is externalized by non-classical secretion pathways from activated tumor ECs, where it is deposited in the tumor cell-vasculature interface and used by ECs to support of migration and formation of new vasculature." (PMID 35606362, 2022). "Clearly, both WB and IF showed that shRNA silencing CXCR4 synergistically enhanced the effect of PTX treatment on decreasing Akt phosphorylation and the resulting reduction in N-cadherin, vimentin, snail, CD44, CD133, and NANOG protein expression in OVCA420 tumor tissues." (PMID 35681259, 2022). "In terms of FGFR-2 mutation, we found the following correlation p-values: LVI (p = 0.069), expression of vimentin (p = 0.000), tumor budding (p = 0.000), and lack of E-cadherin (p = 0.000), RFS (p = 0.032), ECSS (p = 0.047)." (PMID 36143062, 2022). "Conversely, cells in the center of a tumor mass retain a higher expression of the epithelial markers E-cadherin and cytokeratin and little to no expression of vimentin, a mesenchymal marker." (PMID 36012449, 2022).
tumor (continued). "Vimentin and N-cadherin levels were upregulated after LINC00909 overexpression, while E-cadherin levels were attenuated, suggesting that LINC00909 activates EMT to enhance tumor metastasis." (PMID 36262353, 2022). "Immunohistochemical staining showed that the tumor cells were positive for vimentin and Bcl-2 but negative for S-100, desmin Syn, WT-1, EMA, CD34, and CD99; the Ki-67 index in tumor cells was 40%." (PMID 36482604, 2022). "Out of the 34 pre-treatment ALK-rearranged NSCLC tumor specimens, 18 (53%) lacked vimentin expression and 16 (47%) expressed vimentin." (PMID 35042943, 2022). "Indeed, SN-exo transfer dramatically reduced E-cadherin expression and boosted the expression of Vimentin and ZEB1, rendered tumor cells a mesenchymal, spindle-like morphology." (PMID 36302751, 2022). "Indeed, examining the protein extract of the tumor tissues, we found that that the WT/PyMT tumors expressed increased levels of the smooth muscle α (α-SMA) protein and vimentin compared to the 211F/PyMT tumors." (PMID 35628489, 2022). "Similarly, It was also found that oxymatrine in combination with 5-Fu treatment efficiently regulated tumor cells EMT through effective modulation of the expressions of Snai2, vimentin, E-cadherin, and p-NF-κB p65 in HCT-8/5-Fu cells." (PMID 35308223, 2022). "Importantly, knockdown of Tspan6 was sufficient to trigger an EMT in Ras-transformed mouse mammary epithelial cells and in in vivo tumor experiments we also observed an EMT, as defined by altered Vimentin and E-Cadherin expression, in Tspan6 knockdown cells." (PMID 35184157, 2022). "Furthermore, biglycan downregulates the expression of the tumor-suppressor gene, PTEN (p ≤ 0.01), and increases the expression of endothelial–mesenchymal transition (EMT) and aggressiveness markers vimentin (p ≤ 0.01) and fibronectin (p ≤ 0.01) in MG63 cells." (PMID 35267503, 2022). "The results showed that the expression of EMT-related interstitial proteins (Vimentin, N-cadherin, Snail, and FN1) was significantly decreased in the shCOPB2 group, suggesting that COPB2 knockdown significantly inhibited EMT transformation and tumor invasion." (PMID 35600351, 2022). "Given the potential interaction of PSEN1 with the cytoskeleton protein vimentin which is involved in mediating epithelial- to- mesenchymal transition (EMT) and metastasis, we thus interrogated the involvement of PSEN1 in tumor invasiveness." (PMID 36059511, 2022). "In addition, compared with the CON group, the expression level of vimentin in the HIIE group also had a tendency to increase (P=0.07), which indicates that HIIE tends to induce EMT in tumor cells." (PMID 35371324, 2022). "Tumor cells were negative for vimentin while stromal cells surrounding tumors were highly positive for this marker." (PMID 36333737, 2022). "Tumor cells within the lymph node metastases showed positive staining for e-cadherin in 75% and for cyclin D1 in 49% of the cells but were negative for vimentin in 13 out of 16 cases (81.3%)." (PMID 34495397, 2022). "Our current data show that extracellular endothelial vimentin is targetable in tumors regardless of tumor cell-intrinsic vimentin expression levels." (PMID 35606362, 2022). "Transcription factors such as Snail and vimentin and pivotal signaling pathways, including TGF-β/Smad pathway and AKT1/mTOR pathway involved in EMT, were found to be regulated by circRNAs in tumor cells." (PMID 35538537, 2022). "Our data showed that ORP5 facilitated EMT process by increasing N-cadherin, Vimentin and Fibronectin expressions and inhibiting E-cadherin protein expression, indicating that ORP5 could promote EMT and thereby promote tumor migration." (PMID 35449154, 2022). "The pathohistological analysis revealed that the tumor cells had a slightly pleomorphic round or oval nucleus Hemotoxin & Eosin (HE) and were positive for S-100, neuron specific enolase (NSE), cytokeratin (CK), periodic acid–Schiff (PAS), and vimentin." (PMID 38983526, 2022).
tumor (continued). "We also examined the protein level of tumor tissues in two groups, which showed that PHGDH and pathway-related indicators β-catenin, c-myc, cyclin D1, PCNA, Bcl2, N-cadherin, vimentin, and Snail expression level were lower and BAX and E-cadherin higher in CBR-5884 group." (PMID 36105480, 2022). "Evaluating the zonal staining within the tumor, positive staining for vimentin was restricted to the front of invasion in all cases, not the center of the tumor." (PMID 34495397, 2022). "In G3 samples, CD24 and laminin were lower in Patient 4 and in contrast to the other G3 samples, while vimentin was higher in Patient 3, ECAD higher in Patient 2 and CK20 higher in Patient 4 relative to those in the non-tumour tissue and in contrast to the other G3 samples." (PMID 36362433, 2022). "Unlike vimentin, Cx43, and E-cadherin, an increased amount of tumor cells did not alter the expression of emmprin." (PMID 36552039, 2022). "Here, were noted the results as follows: LVI (R = 0.2181, p = 0.069), expression of vimentin (R = 0.8199, p = 0.000), tumor budding (R = 0.6407, p = 0.000), and lack of E-cadherin (R = 0.6948, p = 0.000)." (PMID 36143062, 2022). "A negative control blood sample from a mouse without a tumour was also examined and no VIM+ or KRT+ cells were identified." (PMID 35493092, 2022). "Immunofluorescent, Western Blot, and qPCR showed that C8018‐7840 notably decreased CCL18‐PITPNM3 induced vimentin and recovered CDH1 expression, which further confirmed that C8018‐7840 inhibited PITPNM3 dependent tumor metastasis." (PMID 36285700, 2022). "The tumor tissues were used to detect the expression levels of TWIST2, E-cadherin, and vimentin." (PMID 36111260, 2022). "Additional studies with the vimentin knockdown OSCC-derived cells suggested a role of vimentin in modulating the expression of K5/K14, mediated partly through ΔNp63 to favor a dedifferentiated phenotype that can promote tumor progression." (PMID 35207438, 2022). "In addition, the previous study reported that SPTs exhibit neuroendocrine differentiation and in these tumor tissues the author also observed chromogranin A, CA19-9, and vimentin which are used to diagnose pNENs." (PMID 36271376, 2022). "The well-differentiated cells within the tumor mass do not express vimentin, and abundant, stable membranous E-cadherin/β-catenin adhesions are maintained as evidenced by high levels of phosphorylated E-cadherin supporting this association." (PMID 36012449, 2022). "Our protein library contained 17 proteins in the context of an infection (CMV, HPV, EBV, HBV, mumps, LPS), tumor and cellular stress response (HSP27, HMGB1, CRT, HO-1, HO-2, IL8), autoimmunity (insulin, collagen, vimentin, albumin) or others (ovalbumin, bovine serum albumin)." (PMID 36429087, 2022). "In agreement with this, we observed that the acinar ADC LF01 primary tumor expressed vimentin in the stroma fibers, but not in the tumor cells." (PMID 34198671, 2021). "Additionally, the representative proteins, in the tumor EMT process including MMP-2 and vimentin, were evaluated via western blotting." (PMID 34162396, 2021). "First, we categorized clustered data into tumor and stromal populations using a panel of markers for each (epithelial: AQP1, AQP2, EPCAM; endothelial: PLVAP, CD31, CD34; fibroblast: PDGFRα, PDGFRβ; immune: CD45; tumor cell: CXCR4, VIM, KRT18, PAX8, PAX2, CA9, CD10)." (PMID 34884982, 2021). "Also, the results of the analysis of tumor tissues revealed that the E-cadherin expression was upregulated, while the Slug, MMP-9, and vimentin expressions were down-regulated." (PMID 34073059, 2021). "This process of BHRF1+/SNHG8 high/miR-512-5p low/TRIM28high in EBVaGC directly enhances the activation of a set of tumor-promoting factors, such as proliferation-related genes (BCL-2, CCND1, PCNA, PARP1) and metastasis-related genes (Snail, VIM, CDH1, and CDH2)." (PMID 34722282, 2021).
tumor (continued). "The neoplasm was mainly composed of round, uninucleate cells with hyperchromatic nuclei, which were immunopositive for OLIG2, doublecortin, MAP2, synaptophysin, and vimentin, indicating components of both oligodendroglial and neuronal differentiation." (PMID 34977226, 2021). "For instance, LF05 and LF15 expressed vimentin in tumor cells other than stroma, while LF29, which was poorly differentiated, only expressed it in the stroma of the primary tumor." (PMID 34198671, 2021). "Besides, EMT-related proteins vimentin and MMP9 were up-regulated, and the proteolytic activity of MMP was enhanced in tumor metastasis." (PMID 33672529, 2021). "In the present study, MALAT1 upregulation in EOC cells was correlated with significantly higher levels of p-PI3K, p-AKT, cyclin D1, vimentin, YAP, and ZEB2, combined with a reduction of E-cadherin expression, thus promoting tumor cell proliferation and metastasis." (PMID 34638541, 2021). "In IHC examinations performed for differential diagnosis, while vimentin, smooth muscle actin, myoglobin, and positive reaction in tumor cells are expected, a negative result is obtained with factor VIII-related antigen, epithelial membrane antigen, and CD34." (PMID 33355800, 2021). "Compared with A375 cells, A375 xenograft tumor displayed an upregulation for glial and neuronal genes (GFAP, BDNF, MAP2, MTURN, ROBO2, SYT1 and TUBB3) and neural stemness genes (ASCL1, MSI1, PAX6, PDGFRA, SOX9, VIM, ZIC1/2)." (PMID 33468253, 2021). "They analyzed GSC derived from primary tumor samples by mass cytometry, and the GSC expressed normal levels of NK cell activation receptor ligands (ULBP2, ULBP3, VIM) and upregulated levels of NK cell inhibitory receptor ligands (HLA-A, HLA-B, HLA-C, HLA-E, HLA-G, PCNA) compared with non-GSC." (PMID 34638384, 2021). "Compared with the control group, the xenograft tumours from mice treated with CVB exhibited an evident decrease in the levels of IGFBP3, p-AKT, p-STAT3, p-ERK, p-JNK, p-P38, Bcl-2, Snail, and Vimentin, while the levels of cleaved Caspase 3 and E-cadherin were increased." (PMID 34512163, 2021). "In addition, IHC staining of mouse tumour tissues showed that the protein expression of PCNA, Bcl2, vimentin, p-PI3K, and p-AKT was reduced, which was consistent with the results of the in vitro studies." (PMID 33995637, 2021). "Given that matrix metalloproteinase (MMP) family proteins and EMT-related proteins participate in tumor cell migration and invasion, we examined the transcript and protein level of MMP9, N-cadherin, Vimentin, and E-cadherin in cells with modified PLAGL2 expression levels." (PMID 33391500, 2021). "The tumor cells were negative for PD-L1 or vimentin with both the cutoff values in the majority of patients." (PMID 34917615, 2021). "In the HPV negative tumor group (n = 11), vimentin expression correlated strongly with Ktrans max (r = 0.76, p = 0.007) as well as with Kep max (r = 0.65, p = 0.03)." (PMID 34801089, 2021). "In addition, the tumor cells were also positive for AE1/AE3 (2/2), CEA (3/3), EMA (1/1) and vimentin (2/2)." (PMID 34838061, 2021). "Since we observed that MDA-MB-468 can induce vimentin under hypoxia, we assumed that MDA-MB-468 might contain a subpopulation of tumor cells that may acquire mesenchymal attributes under cell stress." (PMID 33540545, 2021). "The tumor was positive for CK AE1/AE3, Vimentin, S100 and Brachyury." (PMID 34717660, 2021). "In line with the primary tumour, cultured cells maintained expression of pancytokeratin as well as vimentin while actin was consistently not expressed." (PMID 33727576, 2021). "Tumor cells were positive for CD21, CD35, CD68, vimentin, and EGFR." (PMID 34516525, 2021). "Immunohistochemical testing is useful for confirming the histopathological diagnosis, with tumor cells that are diffusely positive for vimentin, focally positive or negative for α-smooth muscle actin, and preferably negative for other markers." (PMID 33829348, 2021).
tumor (continued). "Moreover, compared to tumor tissue formed from control cells, the tumor tissue formed from SKOV3/miR-320a cells in mice showed less E-cadherin staining and higher vimentin signal." (PMID 33718138, 2021). "In addition, QFG treatment inhibited EMT and induced autophagy progression in CRC tumor cells, including that QFG upregulated the expression of E-cadherin, beclin-1, and LC3-II, but downregulated the expression of N-cadherin, vimentin, TWIST1, and p62." (PMID 34887935, 2021). "Overall, PDAC cells in the presence of CAF cells were more sensitive to STAT3 and Ref‐1 inhibition, with the greatest tumour reduction present in combination treatment, and no reduction in the CAFs as determined by vimentin and Masson's trichrome." (PMID 33274592, 2021). "Among 23 phenotypes of CTCs, the number of CTCs in three populations increased with an increase in the size of the primary tumor: CD45–EpCAM+CK7–Snail–N-cadherin–Vimentin–, CD45–EpCAM+CK7–Snail–N-cadherin–Vimentin+, and CD45–EpCAM–CK7+Snail–N-cadherin–Vimentin–." (PMID 33801519, 2021). "Moreover, the miR-199b-5p expression was remarkably reduced in the xenograft tumours, along with the downregulated expression of E-cadherin and the upregulated expression of DDR1, vimentin and fibronectin." (PMID 33239676, 2021). "Immunohistochemical staining for vimentin showed positive staining for stromal cells, not tumor cells, and significantly higher vimentin expression in GBCs of Cluster B than in GBCs of Cluster A (p = 0.0003308 by Mann–Whitney U test)." (PMID 33578820, 2021). "When the authors exposed human MSCs to tumor cell-conditioned medium for 30 days, markers of CAFs (such as vimentin, FSP, α-SMA, or CXCL12) increased, supporting the hypothesis of tumor cell-mediated MSC differentiation towards a protumoral CAF state." (PMID 33530455, 2021). "Vimentin is one of the major constituents of the intermediate filament protein family and helps coordinate different signal transduction pathways, inducing EMT in tumor cells." (PMID 34513994, 2021). "Upon immunohistochemistry, the tumor cells stained positive for vimentin and Pax-8, whereas they were negative for CK7 and Ca19-9, and were therefore diagnosed as ccRCC metastases." (PMID 34059139, 2021). "Tspan5 correlation analyses of TCGA tumour samples revealed that Tspan5 expression is positively correlated with the expression of ADAM10, Notch1, Notch2, Notch3, Notch4, Hey1, vimentin, N‐cadherin and Snail, whereas it is negatively correlated with E‐cadherin in HCC tissues." (PMID 33955149, 2021). "The LINC01010 can inhibit the proliferation and migration of HCC cells by interacting with vimentin, suggesting that LINC01010 may function as a tumor suppressor and a potential target for treatment." (PMID 34830378, 2021). "At recurrence, hematoxylin and eosin (H&E) staining revealed mainly spindle-shaped tumor cells diffusely positive for vimentin but negative for E-cadherin." (PMID 34257602, 2021). "Western blot showed that the protein expression levels of FSTL3, Vimentin, N-cadherin, MMP2 and MMP-9 in the mice tumor tissue in the sh-LBX2-AS1 experimental group were decreased, indicating that FSTL3 expression was increased at protein level and EMT was promoted." (PMID 34858481, 2021). "Moreover, Vimentin and CD133 tumor expression were also evaluated in 36 samples from patients with EGFRm NSCLC in order to validate in vitro results." (PMID 34771484, 2021). "Moreover, EXO facilitated the EMT in the tumor xenograft model mice after irradiation, manifesting as the upregulations of ZEB1, N-cadherin, β-catenin, and vimentin, and the downregulation of E-cadherin." (PMID 34462422, 2021). "In order to validate the functional enrichment analyses, we performed phosphorylated ERK1/2 (pERK1/2) IHC, as well as pan-cytokeratin (CK) and vimentin (VIM) IHC, to demonstrate downstream MAPK pathway activation and EMT reprogramming of tumor cells, respectively." (PMID 34493785, 2021).